MIF (macrophage migration inhibitory factor)
Diseases named in the same sentence as MIF in open-access papers (continued):
Sharing a sentence is not in itself a finding about the gene and the disease.
tumor (continued). "In concordance with the L-R analysis, the image-based assays indicated the interacting cells mediated by CXCL10/CXCR3 and MIF/CD74 more closely co-localized with each other in tumor tissues as compared to those in NTL tissues." (PMID 35933472, 2022). "Overexpression of MIF in bevacizumab-resistant GBM xenograft models resulted in decreased tumor weight, decreased GAMs, increased M1/M2 ratio, and decreased angiogenesis." (PMID 36013403, 2022). "MIF level in BC tissue is also positively correlated with IL-8 expression and tumor microvessel density (MVD)." (PMID 35842634, 2022). "Our study showed that pharmacological targeting of MIF with 4-IPP delayed NB tumor growth, improving overall survival in LAN-1 xenograft models." (PMID 35715791, 2022). "EVs, MIF axis and TA-MSCs form a positive feedback loop with tumor cells, which influences the occurrence and development of tumors." (PMID 35842634, 2022). "In GBM, a correlation was seen between high levels of MIF and tumor recurrence, which is confirmed also by our data." (PMID 35216175, 2022). "Specific to MIF signaling in tumor tissue, CellChat identified ligand MIF and its multi-subunit receptor CD74+CXCR4 as the most significant signaling, contributing to the communication from CD4+ T cells to CD8+ T2 and CD8+ T3 cells." (PMID 35812372, 2022). "MIF is a pro-inflammatory cytokine widely expressed by bone marrow-derived macrophages, vascular endothelial cells, tissue epithelial cells and some tumor cells." (PMID 35165294, 2022). "In terms of promoting tumor drug resistance, TA-MSCs, TA-MSCs-EVs and MIF can promote tumor drug resistance by activating the same signaling pathway and regulating similar related protein expression, such as STAT3, MAPK, Bcl etc." (PMID 35842634, 2022). "More importantly, inhibition of either MIF or SLC3A2 in vivo significantly promoted the apoptosis of tumour cells, and especially in cells co‐transfected with shMIF and shSLC3A2." (PMID 35567291, 2022). "Following ingestion, MIF small-molecule inhibitors suppress the functions of TA-MSCs and tumor cells by blocking MIF signaling and the positive feedback loop, thus inhibiting tumor progression." (PMID 35842634, 2022). "Further, while we highlight that tumor-conditioned media can reactivate trained myeloid cells, we also identify a specific factor, MIF, in the tumor-conditioned media that is involved in this activation." (PMID 35140221, 2022). "In a mouse model of BC, MIF depletion led to an increase in the abundance and activation of DCs, further confirming that MIF mediates tumor growth promotion through DCs inhibition." (PMID 35842634, 2022). "Extensive evidence supports a stimulatory role of MIF in tumor progression although a few studies have described an inhibitory effect." (PMID 35842634, 2022). "The collective studies clearly demonstrate that TA-MSCs, TA-MSCs-EVs and MIF drive proliferation, migration and invasion of tumor cells through direct information exchange between cells." (PMID 35842634, 2022). "MIF has been reported to be involved in the development and progression of a variety of tumours, and we next addressed the role of MIF in PDAC progression in vivo." (PMID 36703790, 2022). "We found that MIF was significantly upregulated in LUAD tumor tissue compared to normal samples, and a high expression of MIF was correlated with poor prognosis of LUAD patients." (PMID 35311093, 2022).
tumor (continued). "Studies have shown that TA-MSCs, TA-MSCs-EVs and MIF affect the proportion balance of Th phenotype and promote the transformation of Th into promote tumor Th2 phenotype, however, the specific mechanism of action remains to be elucidated." (PMID 35842634, 2022). "Specifically, the chemokine macrophage migration inhibitory factor (MIF) contained in tumor-derived exosomes led to the release of TGF-β by KCs, which in turn acted on HSCs, resulting in the production of FN and retention of additional BMDCs in the liver." (PMID 35740692, 2022). "Further analysis showed that ligand-receptor pairs, including MIF − (CD74 + CXCR4), MIF − (CD74 + CD44), MDK–NCL and LGALS9 − CD45, etc. mediated the communication between m6A associated subtypes of TME cells and tumor epithelial cells." (PMID 35509079, 2022). "Macrophages secrete cytokines involved in tumor progression such as macrophage migration inhibitory factor (MIF), IL-8 and TNFα." (PMID 35328127, 2022). "Our findings suggested that the tumor-promoting interaction between the BM microenvironment and NB cells is mediated, in part, by the MIF/CXCR4 signaling axis." (PMID 35715791, 2022). "We found that inhibition of MIF or SLC3A2 expression in vivo markedly suppressed the growth of tumours, and the inhibitory effect was even more significant in the co‐transfection group." (PMID 35567291, 2022). "The presence of CD74 protein on tumour cells membranes and cytoplasm in our study suggests an interaction with macrophage migratory inhibitory factor (MIF) and internalisation of CD74, in agreement with other studies." (PMID 35208514, 2022). "In other studies, in head and neck squamous carcinoma, the HIF-1α–MIF axis contributed to the recruitment of myeloid (CD11b+-Gr-1+) cells to enhance tumor growth and angiogenesis." (PMID 36496973, 2022). "We found CAFs which highly expressed CTHRC1 (from F04 and F08) and tumor associated macrophages were mediated by a different set of ligand-receptor pairs, including THY1/aXb2 complex, GRN/TNFRSF1A, CD99/PILRA, CD74/MIF, APP/CD74, ANXA1/FPR1, etc." (PMID 35928443, 2022). "MIF enhances tumor angiogenesis through activating the MAPK signal pathway by enhancing phosphorylation of p38-MAPK and p44/42 and expression of VEGF-C in BC cells." (PMID 35842634, 2022). "Follow-up studies indicate that lung injury induces an increase in MIF expression, which protects lung cancer cells from apoptosis and promotes tumor proliferation." (PMID 35842634, 2022). "We further investigated the communication strength within tumor subclones and also found the significant difference in MK and MIF signalling pathways." (PMID 35322584, 2022). "The tumor-promoting role of macrophage migration inhibitory factor (MIF) in the immunosuppressive TME has also been revealed." (PMID 35842634, 2022). "MIF is a pro-inflammatory cytokine, aberrantly expressed in many solid tumours, including breast, and it has been shown to promote tumour progression and metastasis." (PMID 35012533, 2022). "CPSI-1306 as a MIF inhibitor was found to decrease tumor growth and metastasis both in vitro and in vivo." (PMID 35963853, 2022). "Recent experiments suggest that MIF is significantly correlated with the proportion of CSCs in tumor tissues." (PMID 35842634, 2022). "Emerging evidence has indicated that MIF is an important link between inflammation and malignant progression in the tumour microenvironment." (PMID 35060345, 2022). "MIF has been confirmed to contribute to a variety of facets of tumor growth, including cell proliferation, differentiation, and angiogenesis." (PMID 35967424, 2022). "Serum MIF levels, an important modulator in tumor angiogenesis, were decreased in both Smeg and rSmeg-hMIF-hIL-7 compared with PBS, but rSmeg-hMIF-hIL-7-cells showed the most pronounced reduction in MIF levels compared with Smeg." (PMID 34389619, 2021).
tumor (continued). "In cancer cells from CRC patients and in an acute colitis-CRC mouse model, a tumor-specific elevation of MIF expression was demonstrated." (PMID 34744751, 2021). "In this study, we aimed to develop a therapeutic vaccine capable of inhibiting tumor development by inducing anti-MIF immune responses." (PMID 34389619, 2021). "Here the authors reveal that the macrophage migration inhibitory factor (MIF) functions as 3’ flap nuclease involved in resolving replication stress affecting overall tumor progression." (PMID 34012010, 2021). "MIF is triggered by autocrine and paracrine signals by the tumor, and its expression level increases with the higher-grade tumors." (PMID 34516577, 2021). "Of note, human MIF (huMIF) induces tumor growth and metastasis by inducing MDSC in the tumor, which promotes immunosuppression in the tumor’s microenvironment." (PMID 34684226, 2021). "The macrophage migration inhibitory factor (MIF) receptor CD74 is overexpressed in various neoplasms, mainly in hematologic tumors, and currently investigated in clinical studies." (PMID 34671548, 2021). "In contrast, we found a significant positive correlation between EBER1 levels and MIF expression levels in tumor nests." (PMID 34407796, 2021). "Nevertheless, MIF is known to act as chemokine on tumor-specific macrophage recruitment and/or macrophage polarization, and macrophages are known to secrete angiogenic factors, further promoting CRC tumorigenesis." (PMID 33542244, 2021). "MIF is a pleiotropic cytokine that regulates inflammation, cell proliferation, and differentiation, and also promotes tumor cell proliferation, angiogenesis, and metastasis by activating the STAT3, ERK, and PI3K/AKT signaling pathways." (PMID 33431808, 2021). "MIF acts as an immobilizer of macrophages in the tumor site, in transition from epithelial to mesenchymal cells always in the tumor site and reversed in the bloodstream to allow the implant of metastases." (PMID 34944856, 2021). "Of these, ADM, DCBLD2, EREG, ITGA5, MIF, MMP14, and TREM1 were associated with poor prognosis and significantly increased in tumor, while BTG2 was related to favorable prognosis and decreased in tumor." (PMID 35002712, 2021). "We then performed orthotopic implantation of parental and MIF KO1 and KO2 MDA-MB-231 cells into the mammary fat pad of NOD/SCID mice, respectively, to examine the effect of MIF on tumor growth in vivo." (PMID 34012010, 2021). "MIF is involved in inflammatory and immune responses (pro-inflammatory), in cell growth (tumor, embryo, wound healing), and has an essential role in activating T cells after mitogenic or antigenic stimuli." (PMID 33478018, 2021). "The MIF score of NPC cells in the tumor nest was significantly higher than those of the epithelial and non-epithelial tissues of inflammation cases." (PMID 34407796, 2021). "Because increased MIF secretion promotes tumor cell survival, inflammation, and angiogenic complications, these reports highlight the benefits of adjuvant MIF inhibition to exhibit the full potential of anti-cancer therapy." (PMID 34516577, 2021). "MIF is produced by glioblastoma tumour cells including GSCs, and levels are significantly enhanced under hypoxia." (PMID 33803414, 2021). "Similar to the patient tumors, established AOM/DSS-induced tumors confirmed tumor-specific elevation of MIF expression." (PMID 33542244, 2021). "In summary, our study showed that MIF and DDT are promising targets for overcoming radio-resistance in association with treatment and tumor recurrence." (PMID 34516577, 2021). "We found a significant positive correlation between EBER1 levels and MIF expression levels in tumor nests (r = 0.305, p = 0.007)." (PMID 34407796, 2021). "Collectively, rSmeg-hMIF-hIL-7 enhanced cell-mediated immune responses against MIF and regulated the MIF-mediated PI3K/Akt pathway in the tumor environment via functional TILs." (PMID 34389619, 2021).
tumor (continued). "Our data support that tumor-specific stabilization of MIF promotes CRC progression and allows MIF to become a potential and selective therapeutic target in CRC." (PMID 33542244, 2021). "Mechanistically, Mif-containing tumor cells regulate angiogenic gene expression via a MIF/CD74/MAPK axis in vitro." (PMID 33542244, 2021). "Intriguingly, epithelial cancer cells express high levels of MIF compared to those in the normal surrounding epithelium, indicating that the major source of MIF is tumor epithelial cells." (PMID 33542244, 2021). "At present, it is generally believed that MIF promotes tumor growth through various mechanisms, not only in cancer cells but also nearby and even distant cancer cells and noncancer cells." (PMID 35036405, 2021). "Concomitantly, we also showed within this model that MIF regulates overall inflammatory signatures but especially during tumor initiation." (PMID 33542244, 2021). "We found a significant positive correlation between EBER1 levels and MIF levels in tumor nests and a significant positive correlation between HPV16/18 and CD11c(+) cell levels in NPC tissues." (PMID 34407796, 2021). "Our results showed that MIF expression in tumor nests was higher than those in the tumor stroma of NPC and inflammation tissues." (PMID 34407796, 2021). "MIF reduced tumor-derived organoids show a reduced antitumor response to Hsp90 interference compared to that in Mif-proficient organoids, indicating that MIF is an important Hsp90-stabilized protein in CRC." (PMID 33542244, 2021). "Astrocytes in the tumor microenvironment are activated by tumor cell-derived factors, such as the macrophage migration inhibitory factor (MIF), IL-8, and plasminogen activator inhibitor-1 (PAI-1)." (PMID 33466236, 2021). "In a sense, this part of our data was consistent with the MIF-dependent tumor-promoting phenotypes reported in literature.Those differentially expressed marker genes between the two clusters also suggested potential upstream regulators of MIF transcription." (PMID 34268123, 2021). "Activated T cells secrete a MIF factor that has impact on cell mitosis and initiate transformation of cells to malignant phenotype, thereby facilitating tumor progression." (PMID 34157052, 2021). "MIF is normally involved in leucocyte recruitment and liver inflammation leading to fibrosis, but here, the authors demonstrated that MIF in PDA tumor cells derived-EVs targets KCs, stimulating their secretion of pro-inflammatory cytokine." (PMID 34207163, 2021). "We found that DE-MaRGs were enriched in the chaperone complex, which is consistent with a previous study reporting that tumor-activated HSP90 chaperone complex can protect MIF from degradation." (PMID 34120619, 2021). "The heat shock protein 90 (HSP90) chaperone machinery stabilizes and protects MIF from degradation and supports tumor progression via macrophage recruitment and angiogenesis." (PMID 34744751, 2021). "These MDSC functions can be reduced upon interference of MIF signalling, with effector T cell responses significantly enhanced in tumour-bearing mice with attenuated MIF." (PMID 33803414, 2021). "Poly(ADP-ribose) polymerase 1 co-localizes with MIF to the DNA replication fork, where MIF nuclease activity is required to resolve replication stress and facilitates tumor growth." (PMID 34012010, 2021). "As rSmeg-hMIF-hIL-7 administration decreased MIF level in serum and tumor, immune cells population in tumor microenvironment were changed." (PMID 34389619, 2021). "Further investigation found that JNK mediated macrophage activity via extracellular matrix metalloprotease inducer (EMMPRIN) and macrophage migration inhibitory factor (MIF) expressions in tumor cells." (PMID 34063627, 2021). "The MIF score in the tumor nest was significantly higher than that in the tumor stroma of the NPC tissues." (PMID 34407796, 2021).
tumor (continued). "The possible mechanism of resistance to anti-angiogenic therapy can be bevacizumab-induced reduction of MIF expression in cancer cells resulting in the expansion of M2 macrophages, which in turn promotes tumor growth." (PMID 34209679, 2021). "HGF and MIF were also upregulated in HCC tissues compared with those in para-tumor tissues, and predicted poor prognosis of HCC patients." (PMID 33658044, 2021). "MIF has been extensively studied in relation to malignancy and its effects are thought to occur mainly through alteration of the tumor microenvironment." (PMID 34109216, 2021). "Taken together, these results confirm an enhanced tumor-specific increase in MIF occurrence within the epithelial tumor compartment." (PMID 33542244, 2021). "To exploit further therapeutically targeting of stabilized MIF, we administered Hsp90 inhibitors to healthy epithelial/mucosal-derived and tumor-derived murine colonic organoids from the same AOM/DSS-induced mice (i.e., matched pairs)." (PMID 33542244, 2021). "The expression of PDL-1 was regulated, and MIF also facilitated the tumor cells’ escape immune surveillance." (PMID 33819196, 2021). "In summary, since MIF stabilization is a crucial event, specifically in tumor cells, Hsp90 inhibition provides a potential approach to target MIF function in CRC." (PMID 33542244, 2021). "Measurement of MIF expression in murine tumor lysates indicated increased MIF expression in tumors compared to normal colonic tissue." (PMID 33542244, 2021). "In tumors, the major source of MIF is the epithelial cells themselves, followed by a minor secretory contribution from constituents of the tumor microenvironment, such as stromal and inflammatory cells." (PMID 33542244, 2021). "Pharmacological inhibition of HSP90 to reduce MIF levels decreased tumor growth in vivo, and selectively reduced the growth of organoids derived from murine and human tumors without affecting organoids derived from healthy epithelial cells." (PMID 33542244, 2021). "Correlations between MIF and E-cadherin and invasion area and histological grading of tumor tissue which has grown through the prostate." (PMID 34157052, 2021). "Macrophages have been shown to secrete cytokines involved in tumor progression such as macrophage migration inhibitory factor (MIF), IL-8 and TNFα." (PMID 34682791, 2021). "We found that rSmeg-hMIF-hIL-7 treatment led to a significant cancer inhibitory effect mainly by restoring the CTL response in tumor microenvironments by inducing anti-MIF immune responses." (PMID 34389619, 2021). "Although there was no statistical significance between NPC subgroups by using Kruskal-Wallis test, MIF scores in tumor nest showed the trend as EBV+/HPV+ > EBV+/HPV- > EBV−/HPV-." (PMID 34407796, 2021). "Recently, the PRMT6-ILF2 axis has been shown to be responsible for tumor progression and induction of pro-tumorigenic cytokine expression (MIF, IL8)." (PMID 34208043, 2021). "Further investigation is required to understand if MIF’s nuclease activity contributes to inflammation and immune response and their impact on tumor growth." (PMID 34012010, 2021). "The extent of MIF expression is dependent on the tumor tissue type, stage, and grade among other factors." (PMID 33324425, 2020). "Both groups of mice developed tumors and on the arrival of endpoints, MIF-depleted MIF-sh1 xenograft tumors showed significantly reduced tumor volume and tumor weight compared to scr xenograft tumors." (PMID 32943608, 2020). "Numerous studies show that high MIF levels are found in almost all types of human cancers and are likely to be involved in all stages of tumor development." (PMID 32963755, 2020). "Subsequent studies found that tumor-derived MIF increases the expansion and migration of anti-tumor Th17 cells in nasopharyngeal carcinoma through CXCR4 which ultimately was associated with a more favorable clinical outcome." (PMID 33324425, 2020).